SND1 (staphylococcal nuclease and tudor domain containing 1)
Diseases named in the same sentence as SND1 in open-access papers (continued):
Sharing a sentence is not in itself a finding about the gene and the disease.
lung carcinoma (7 papers, 2014 to 2025). "Therefore, potential molecular mechanisms underlying the modulation of lung cancer resistance conferred by SND1 need to be uncovered." (PMID 39885142, 2025). "Additionally, the expression of PDCD4 (a tumor suppressor highly associated with lung cancer) in NSCLC cells with low endogenous levels was attenuated by SND1 silencing, implying that SND1 might function as a molecular regulator upstream of PDCD4." (PMID 39885142, 2025). "In addition, we report several novel gene combinations (H1: CDCA7L-MLLT3, P3: SND1-TMEM178B), of which individual fusion partners have been previously reported in the context of several cancers, including MLLT3 in leukemia, SND1 (staphylococcal nuclease and tudor domain) in lung cancer." (PMID 32414213, 2020). "Using a whole gene capture strategy for formalin-fixed, paraffin-embedded (FFPE) DNA samples, we identified two additional never smoker lung cancer cases from the same cohort also carrying the SND1-BRAF fusion (Y59 and Y69)." (PMID 25985019, 2015). "As a typical example, in a lung cancer we identified an insertion of all five exons of the gene FOPNL, including a portion of the 5′ UTR, the full coding sequence and the full 3′ UTR, into the eleventh intron of SND1 in the opposite orientation." (PMID 24714652, 2014). "Although the molecular mechanism by which SND1 is overexpressed in cancer is not clear, it has been identified as a target of a number of tumor suppressor miRNAs, such as microRNA-320a in lung cancer, microRNA-361–5p in colorectal and gastric cancer, and miRNA-184 in malignant glioma." (PMID 32258418, 2018). "In order to investigate the role of SND1-BRAF fusion protein, we examined the Raf signaling pathway by transiently expressing the fusion gene product and analyzed the phosphorylation status of the downstream proteins by western blot in the H1299 lung cancer cell line." (PMID 25985019, 2015).
malignant glioma (7 papers, 2015 to 2025). A grade III or grade IV glioma arising from the central nervous system. "On the TS miRNA side, downregulation of miR-184 has been found to promote human malignant glioma by regulating its target SND1, a multifunctional nuclease that is overexpressed in multiple cancers." (PMID 29312571, 2017). "Our current study reveals that miR-320a functions as an important suppressor for the cell proliferation, migration and invasion of malignant gliomas by directly silencing SND1 and β-catenin." (PMID 28160566, 2017). "Our findings demonstrate the potential values of miR-320a, SND1 and β-catenin as prognostic biomarkers and therapeutic candidates for malignant gliomas." (PMID 28160566, 2017). "Staphylococcal nuclease domain-containing 1 (SND1), also known as Tudor-SN or p100 coactivator, and β-catenin are overexpressed in various malignant tumors including malignant gliomas." (PMID 28160566, 2017). "Our findings also indicate that miR-320a downexpression is an important cause leading to SND1 and β-catenin overexpressions, and suggest that miR-320a, SND1 and β-catenin are potential therapeutic candidates for malignant gliomas." (PMID 28160566, 2017). "In this study we found higher SND1 mRNA and protein in human malignant glioma tissue as compared to normal brain." (PMID 25405367, 2015). "Our recent studies suggest that SND1 may provide a novel target for malignant glioma treatment." (PMID 25405367, 2015).
ovarian carcinoma (5 papers, 2023 to 2025). A malignant neoplasm originating from the surface ovarian epithelium. "Consistent with this, cProSite data also showed that SND1 abundance is higher in ovarian tumor tissue compared with adjacent normal tissue, reinforcing its potential role in ovarian cancer biology." (PMID 41286067, 2025). "In ovarian cancer, SND1 promotes epithelial-to-mesenchymal transition, which facilitates metastasis of ovarian cancer." (PMID 36669591, 2023). "Moreover, recent studies have also revealed that inhibition of SND1 promoted cisplatin-induced cell death in other cancer cells including bladder and ovarian cancer cells, where the chemotherapy efficacy is generally low, conferring the reversed chemoresistance." (PMID 39885142, 2025). "In the present study, although we did not perform co-immunoprecipitation in ovarian cancer cells, we provide complementary evidence through immunofluorescence staining and confocal microscopy, demonstrating colocalization of MTDH and SND1." (PMID 41286067, 2025).
bladder cancer (4 papers, 2017 to 2025). "Therefore, we preliminarily selected SESN2 as a downstream target regulated by SND1, which has been reported to be downregulated in various cancers and to inhibit bladder cancer progression, but its role in PCa remains unclear." (PMID 40775338, 2025). "Staphylococcal nuclease and tudor domain containing 1 (SND1), a protein with roles in transcriptional activation, RNA splicing, and RNA interference, is reported to be overexpressed in a number of cancers but has not been studied in bladder cancer." (PMID 29207636, 2017).
viral infection (4 papers, 2015 to 2019). "To date, very little research has been performed on deciphering the role of SND1 during viral infections." (PMID 31647415, 2019).
cervical cancer (3 papers, 2022 to 2025). A primary or metastatic malignant neoplasm involving the cervix. "As one of the subtypes of the 14-3-3β protein, circSMARCA5 has been found to inhibit the proliferation and invasion of cervical cancer cells by inhibiting the binding of SND1 and YWHAB." (PMID 35795276, 2022).
clear cell renal cell carcinoma (3 papers, 2020 to 2024). "MTDH promoted the metastasis of clear cell renal cell carcinoma by activating SND1-mediated ERK signaling and epithelial-mesenchymal transition." (PMID 31978894, 2020). "MTDH promoted metastasis of clear cell renal cell carcinoma by activating the SND1-mediated ERK and EMT signaling pathways." (PMID 31978894, 2020). "In addition, SND1 has been demonstrated to promote the metastasis of clear cell renal cell carcinoma by mediating ERK signaling and epithelial–mesenchymal transformation." (PMID 37893001, 2023).
colorectal tumor (3 papers, 2021 to 2024). "Compared with adjacent normal tissues, the expression of SND1 mRNA in colorectal tumor tissues increased significantly." (PMID 34897032, 2021). "The levels of SND1 mRNA were obviously elevated in colorectal tumor tissues." (PMID 35220962, 2022).
gastric cancer (3 papers, 2017 to 2025). A primary or metastatic malignant neoplasm involving the stomach. "By coincidence, our previous study has demonstrated that miR-361-5p inhibits the malignant phenotype of colorectal and gastric cancer by targeting SND1." (PMID 29132384, 2017). "CircSLC4A7 was reported to interact with the HSP90 to accelerates stemness and progress of gastric cancer, and the circMETTL9 was researched as a regulator of neuroinflammation of TBI by complexing with the SND1." (PMID 39962534, 2025).
lung adenocarcinoma (3 papers, 2015 to 2024). A carcinoma that arises from the lung and is characterized by the presence of malignant glandular epithelial cells. "This study reports the high frequency of oncogene mutations and the identification of a novel SND1-BRAF fusion transcript in about 3% of lung adenocarcinoma from never smokers." (PMID 25985019, 2015). "Specifically, the progression of lung adenocarcinoma is induced by the downregulation of low methylation related LINC00987, which inhibits phosphorylation-mediated SND1 degradation." (PMID 39411134, 2024).
melanoma (3 papers, 2019 to 2023). A malignant, usually aggressive tumor composed of atypical, neoplastic melanocytes. "In addition, TARBP2 expression levels were significantly higher in metastases type of melanoma (CMMM) compared to primary melanoma (PCMM), and SND1 expression levels were significantly higher in CMMM compared to PCMM and BMN." (PMID 36982460, 2023).
triple-negative breast carcinoma (3 papers, 2022 to 2025). An invasive breast carcinoma which is negative for expression of estrogen receptor (ER), progesterone receptor (PR), and human epidermal growth factor receptor 2 (HER2). "A small peptide, derived from 393 to 403 a.a. of AEG-1, was shown to inhibit AEG-1/SND1 interaction, and its ability to inhibit in vitro proliferation of triple-negative breast cancer cells was demonstrated." (PMID 40282551, 2025).
endothelial dysfunction (2 papers, 2025). In vascular diseases, endothelial dysfunction is a systemic pathological state of the endothelium (the inner lining of blood vessels) and can be broadly defined as an imbalance between vasodilating and vasoconstricting substances produced by (or acting on) the endothelium. "Since SND1 deficiency leads to endothelial dysfunction, we reasoned that SND1 OE may counteract sunitinib-induced endothelial dysfunction." (PMID 39895626, 2025). "Having shown that SND1 regulates expression of UBE2N in ECs, we tested the notion that UBE2N acts downstream of SND1 and is implicated in sunitinib-induced endothelial dysfunction." (PMID 39895626, 2025). "SND1 inhibition led to endothelial dysfunction, whereas SND1 OE protected against sunitinib-induced endothelial dysfunction." (PMID 39895626, 2025). "Together, these results suggest that the SND1/UBE2N/RNF8-RNF168 axis is crucial in protecting against sunitinib-induced endothelial dysfunction by regulating the DDR pathway." (PMID 39895626, 2025). "Nonetheless, to circumvent these potential concerns, we decided to focus on the direct effects of SND1 on ECs instead and hypothesized that pharmacological reversal of broad transcriptional changes caused by SND1 KD in ECs may protect against sunitinib-induced endothelial dysfunction." (PMID 39895626, 2025). "SND1 regulates endothelial function, and its inhibition leads to endothelial dysfunction." (PMID 40666289, 2025). "It should also be noted that while we focused on the DDR pathway in this study, it is plausible that SND1 may regulate other molecular mechanisms that may co-contribute to sunitinib-induced endothelial dysfunction." (PMID 39895626, 2025). "With this approach, we revealed translational regulation of SND1 as a key mediator of sunitinib-induced endothelial dysfunction, which suggests that targeting SND1 translation and the SND1 downstream factors UBE2N, RNF8, and RNF168 is a potential therapeutic strategy for vascular dysfunction." (PMID 39895626, 2025). "Our study established a central role for translational control of SND1 in sunitinib-induced endothelial dysfunction that could potentially be therapeutically targeted to reduce sunitinib-induced vascular toxicity." (PMID 39895626, 2025). "However, whether and how the SND1/DDR pathway is involved in sunitinib-induced endothelial dysfunction remains enigmatic." (PMID 39895626, 2025).
Hepatic steatosis (2 papers, 2021 to 2024). Steatosis is a term used to denote lipid accumulation within hepatocytes. "Although our previous research shows an ameliorated high-fat diet (HFD)-induced hepatic steatosis and insulin resistance in global SND1 transgenic mice, the involvement of SND1 loss-of-function in hepatic metabolism remains elusive." (PMID 34608846, 2021). "This study reveals a new signaling pathway, Snhg3/SND1/H3K27me3/PPARγ, responsible for hepatic steatosis and provides evidence of lncRNA-mediated epigenetics in the pathophysiology of MASLD." (PMID 39436790, 2024). "Furthermore, inhibition of PPARγ with T0070907 alleviated Snhg3- and SND1-induced Cd36 and Cidea/c increase and improved Snhg3-aggravated hepatic steatosis." (PMID 39436790, 2024). "This suggested that hepatocyte-specific deletion of SND1 is unlikely to modulate the cholesterol level and hepatic steatosis of mice." (PMID 34608846, 2021). "Under the condition of HFD, the absence of hepatic SND1 affects the weight of white adipose tissue, but not the gross morphology, body weight, cholesterol level, liver weight, and hepatic steatosis of mice." (PMID 34608846, 2021).
non-small cell lung carcinoma (2 papers, 2021 to 2025). A group of at least three distinct histological types of lung cancer, including non-small cell squamous cell carcinoma, adenocarcinoma, and large cell carcinoma. "Additionally, TINCR can interact with ATP-Citrate Lyase (ACLY), BRAF, and Staphylococcal Nuclease and Tudor Domain Containing 1 (SND1) in nasopharyngeal cancer, non-small cell lung cancer, and post-burn skin fibroblasts, respectively." (PMID 34057016, 2021).
osteoarthritis (2 papers, 2023 to 2024). A noninflammatory degenerative joint disease occurring chiefly in older persons, characterized by degeneration of the articular cartilage, hypertrophy of bone at the margins and changes in the synovial membrane. "In this study, we first found that SND1 was upregulated in chondrocytes of patients with osteoarthritis." (PMID 37749650, 2023). "In vivo results showed that the damage to cartilage tissue was significantly alleviated in rats with osteoarthritis by knocking down SND1 expression." (PMID 37749650, 2023). "ELISA results indicated that inflammatory factor secretion was reduced in the knee joint cartilage tissues of osteoarthritis rats with SND1 silencing." (PMID 37749650, 2023). "We performed RT-qPCR analysis of knee osteoarthritis cartilage samples (N = 20) and non-osteoarthritis cartilage samples (N = 20) and showed that SND1 mRNA expression was upregulated in the cartilage of osteoarthritis patients." (PMID 37749650, 2023). "TUNEL staining results indicated that osteoarthritis rat knee chondrocyte apoptosis increased, and cell apoptosis decreased after knockdown of SND1." (PMID 37749650, 2023). "Compared with the rats in the model group, the cartilage tissue scores of osteoarthritis rats decreased under the treatment of si-SND1, suggesting that the cartilage damage of rats was alleviated." (PMID 37749650, 2023). "However, the involvement of SND1 in the progression of osteoarthritis is poorly studied, and the specific regulatory mechanisms also require further investigation." (PMID 37749650, 2023). "In addition, the immunohistochemical results suggested that SND1 positive cell numbers was increased in cartilage tissue of patients with osteoarthritis." (PMID 37749650, 2023). "Recently, evidence has suggested a regulatory role for SND1 in osteoarthritis progression." (PMID 37749650, 2023). "Moreover, the protein expression of SND1 was increased in chondrocytes isolated from knee cartilage tissue of patients with osteoarthritis." (PMID 37749650, 2023). "For instance, SND1 promotes degradation of GPX4 by destabilizing HSPA5 mRNA and suppressing HSPA5 expression, thus promoting ferroptosis in osteoarthritis chondrocytes." (PMID 38286993, 2024). "In vivo results showed that SND1 silencing inhibited SND1, PINK1 and BECN1 proteins expression in rat knee cartilage tissues compared with the osteoarthritis rats." (PMID 37749650, 2023). "Furthermore, SND1 silencing reduced AMPK and mTOR phosphorylation levels in knee joint cartilage tissues of osteoarthritis rat." (PMID 37749650, 2023). "Furthermore, knockdown of SND1 expression inhibited MMP13 and promoted collagen II protein expression in osteoarthritis rat knee joint cartilage tissues." (PMID 37749650, 2023).
prostate adenocarcinoma (2 papers, 2022 to 2023). "To investigate the role of Snd1 in the context of autochthonous PC, we utilized PB-Cre4/Ptenfl/fl/ERG mice that develop high-grade prostatic intraepithelial neoplasia and prostate adenocarcinoma as young adults (8–12 months after birth)." (PMID 37973913, 2023).
acute liver failure (1 paper, 2021). Rapid deterioration of liver function causing encephalopathy and coagulopathy. "As SND1 is reported to be linked to inflammatory response, the pathobiological feature of acute liver failure (ALF) is also investigated." (PMID 34608846, 2021). "Our in vivo experimental results suggest a dispensable role of endogenously hepatic SND1 in the HFD-induced insulin resistance or LPS/D-GalN-induced acute liver failure in mice." (PMID 34608846, 2021). "Taken together, the current results suggest that hepatocyte SND1 is unable to contribute to altering hepatic inflammatory tones and tissue damage in acute liver failure of mice." (PMID 34608846, 2021). "We thus sought to investigate the potential effect of SND1 hepatocyte-specific deletion on the LPS/D-GalN-induced acute liver failure of mice." (PMID 34608846, 2021). "Our findings demonstrate a dispensable role of hepatic endogenously SND1 in insulin resistance and acute liver failure." (PMID 34608846, 2021). "Overall, hepatic SND1 is insufficient to alter the phenotypes of hepatic insulin resistance and acute liver failure in mice." (PMID 34608846, 2021). "Here, we aimed at further investigating whether the hepatocyte-specific deletion of SND1 in mice affects the presence of acute liver failure induced by LPS/D-GalN." (PMID 34608846, 2021). "We also investigated whether the hepatocyte-specific deletion of SND1 influences the acute liver failure process by using an LPS/D-GalN-induced mice model of ALF." (PMID 34608846, 2021). "Additionally, we analyzed the potential correlations of SND1 expression with insulin resistance and acute liver failure in the species of humans, mice, and rats, based on a set of GEO datasets." (PMID 34608846, 2021). "In this study, we successfully constructed SND1 liver-specific knockout mice for the first time and investigated the potential role of endogenous SND1 in an HFD-induced liver insulin resistance model and acute liver failure model." (PMID 34608846, 2021). "Although hepatocyte-specific deletion of SND1 does not remarkably influence the presence of acute liver failure, it is still worth a study to further analyze the potential effects of SND1 in the global deletion mice." (PMID 34608846, 2021). "Overall, the hepatic expression of SND1 in pathological models of insulin resistance and acute liver failure remains stable, indicating a dispensable role of endogenous SND1 in nonmalignant hepatocytes." (PMID 34608846, 2021).
aneurysm (1 paper, 2024). Bulging or ballooning in an area of an artery secondary to arterial wall weakening. "CircHipk3 serves a dual role in augmenting macrophage pyroptosis by interaction with Stat3, increase the NLRP3 level, and by binding Snd1 to promote Ptbp1 mRNA degradation to inhibit autophagy, thereby inducing aneurysm formation and progression." (PMID 39601144, 2024).
B cell lymphoma (1 paper, 2025). "However, SND1 was not involved in splicing of RTA, since knockdown of SND1 in B cell lymphoma cells did not lead to changes in spliced RTA transcripts." (PMID 39868828, 2025).
chlamydia infection (1 paper, 2021). "Overall, these data showed a decreased IL-12 production, but a higher IL-10 production pattern in DCs of SND1-/- mice, especially with chlamydia infection." (PMID 33635920, 2021).
chlamydial infection (1 paper, 2021). "In conclusion, the present study has demonstrated that SND1 plays an important role in host defense against chlamydial infection." (PMID 33635920, 2021). "Second, and more importantly, the role of SND1 at different phaces of chlamydial infection and also the host in various genetic backgrounds need to be extensively examined." (PMID 33635920, 2021). "This may be particularly important for understanding the mechanism by which SND1 modulates DC during chlamydial infection." (PMID 33635920, 2021). "Furthermore, the data suggest that SND1 can promote type 1 T cell-protective immunity to chlamydial infection by modulating DC function possibly through direct mechanisms." (PMID 33635920, 2021). "In addition to chlamydial infection, our data may provide insight into the mechanism on the role of SND1 in promoting Th1 or Th17 responses reported in other pathological models." (PMID 33635920, 2021).